CD34 (CD34 molecule)
Diseases named in the same sentence as CD34 in open-access papers (continued):
Sharing a sentence is not in itself a finding about the gene and the disease.
solitary fibrous tumor (continued). "CD34 was negative, suggesting this case was not a solitary fibrous tumor, and the typical vasculature pattern of a solitary fibrous tumor was not seen." (PMID 39544284, 2024). "Strong SMA expression and negative CD34 staining effectively differentiate MPCs from other perivascular myoid tumors, such as solitary fibrous tumors and myofibromas." (PMID 38643070, 2024). "Despite this finding, it is important to highlight that CD34 is expressed in several other soft tissue tumors, including non-lipomatous and lipomatous tumors, such as fat-forming solitary fibrous tumor and ASCLT." (PMID 31041916, 2019). "For instance, CD34-positive immunostaining has also been reported in non-vascular cells within CNS tumors, including solitary fibrous tumor and ganglioglioma, thus limiting the use of CD34 as a specific marker for endothelial cells." (PMID 25881913, 2015). "Positiveness for antigens CD-99 and bCl-2 is similar to that of solitary fibrous tumor; nonetheless, CD-34 varies its reaction and is not inconstantly positive for hemangiopericytoma." (PMID 22499385, 2012). "Hemangiopericytoma and solitary fibrous tumor show strong immunoreactivity for vimentin and CD34, but not EMA." (PMID 22934204, 2012). "Similarly, negativity for neuroendocrine markers (Syn, CgA, and CD56) excludes a pancreatic neuroendocrine tumor.​​ CD34 negativity​​ helps exclude a ​​solitary fibrous tumor." (PMID 41244919, 2025). "Other mesenchymal, nonlipogenic CD34+ neoplasms could also be considered in the differential diagnosis, such as solitary fibrous tumor (SFT) and dermatofibrosarcoma protuberans (DFSP)." (PMID 33802620, 2021). "But these expressions were not decisive in the differentiation between solitary fibrous tumor and pancreatic hamartoma, because CD34 was positive for both tumors, and CD99 and bcl-2 expressions were not elucidated in the previous cases of pancreatic hamartomas." (PMID 26425382, 2015). "The positive immunohistochemistry for CD34 is characteristic (albeit nonspecific) for solitary fibrous tumors (SFT), especially low-grade SFT." (PMID 36805296, 2023). "Variable yet frequent expression of h-caldesmon and desmin further supports the myoid lineage, whereas negative staining for markers such as S100, CD34, and CD31 rules out schwannomas, solitary fibrous tumors, and vascular endothelial lesions, respectively." (PMID 40507464, 2025). "In our case, it is easily to rule out diagnoses of inflammatory myofibroblastic tumor (IMT), aggressive fibromatosis, nodular fasciitis (NF), solitary fibrous tumor (SFT), since it is negative for ALK (5A4), β-catenin, SMA, Desmin, and CD34." (PMID 31311568, 2019). "Because the sensitivity and specificity of these markers is sub-optimal, absence of additional markers, including S100, CD34, MelanA are used to discern meningioma from differential diagnosis of schwannoma, solitary fibrous tumor/hemangiopericytoma (SFT/HPC), or metastatic melanoma, respectively." (PMID 31970090, 2019). "c-KIT, CD34, and S-100 protein is negative in PAMT, which are usually positive in GIST, GIST and solitary fibrous tumor, and schwannoma and neurofibroma, respectively." (PMID 28103839, 2017). "CD117 and CD34 were negative, suggesting against a GIST and solitary fibrous tumor, respectively." (PMID 39544284, 2024). "Furthermore, CD34, S100, Bcl-2, and STAT-6 expression was negative, ruling out the possibility of a solitary fibrous tumor and malignant peripheral nerve sheath tumor (MPNST)." (PMID 32430041, 2020). "However the immunoprofile of the neoplastic cells was typical of a solitary fibrous tumor (negative for EMA, strongly positive for CD34, vimentin and Bcl-2)." (PMID 22805173, 2012). "Negative staining for MDM2 and CDK4, CD34 and STAT6, and c-kit and DOG1 led to the exclusion of dedifferentiated liposarcoma, solitary fibrous tumor (SFT), and GIST, respectively." (PMID 38739347, 2024).
schwannoma (67 papers, 2010 to 2026). A benign, usually encapsulated slow growing tumor composed of Schwann cells. "In classical schwannoma and its variants, there is a notable discrepancy in the reported positive rate of CD34." (PMID 39158355, 2024). "In fact, the differential diagnosis between schwannoma and our case is extremely difficult in aspect of morphologic features; however, the positive findings of ER, desmin, and CD34, with heterogenous loss of Rb1, in IHC contributed to the accurate diagnosis." (PMID 39493459, 2024). "Additionally, CD34 demonstrates diffuse expression in schwannoma but complete loss in the MPNST." (PMID 41281118, 2025). "GISTs are consistently positive for CD117, DOG1, and CD34, whereas schwannomas, as in our case, express S100 and SOX10 while being negative for CD117 and DOG1." (PMID 40507589, 2025). "The tumors showed features of both schwannomas and perineuriomas, co-expressing S100, CD34, and perineurial cell markers." (PMID 40507589, 2025). "In this case, histopathological evaluation demonstrated dense proliferation of spindle- and oval-shaped cells in the submucosal layer, with strong immunoreactivity for S-100 protein and negativity for CD34 and c-kit, confirming the diagnosis of schwannoma." (PMID 40772163, 2025). "Positive staining for S100, SOX10, and CD34, coupled with low Ki67 proliferation index, aligns with typical Schwannoma profiles." (PMID 39507764, 2024). "Immunohistochemical markers including CD117, CD56, CD34, S100, SOX10, Calretinin, Desmin, Vimentin, EMA and smooth muscle antigen are associated with Schwannomas and can be used to confirm their diagnosis." (PMID 39558963, 2024). "Immunohistochemical staining is an important method to distinguish schwannomas from other gastrointestinal mesenchymal tumors, with markers like S-100 protein, CD34, and CD117 being particularly specific." (PMID 39533578, 2024). "Recently, the application of CD34 has been reported to differentiate neurofibromas from schwannomas, neurofibromas are strongly positive for CD34 in contrast to most schwannomas." (PMID 33429765, 2021). "TCs/CD34+SCs are observed in Antoni B zones of schwannomas and have been described in this location as endoneurial fibroblasts or CD34-positive fibroblasts." (PMID 32560571, 2020). "Immunohistochemical studies showed the schwannoma component to be S100+, CD 34- while the neurofibroma component was CD34+, variable S100+." (PMID 26709712, 2016). "In this case, we examined immunoreactivity of neoplastic cells for S100 to differentiate from schwannoma, CD34 to differentiate from solitary fibrous tumour, and HMB45 to differentiate angiomyolipoma." (PMID 25945278, 2015). "Our findings indicate that CD34+ cells exhibit significantly higher reprogramming efficiencies (1.199% ± 0.529), compared to fibroblasts (0.040% ± 0.103), PBMCs (0.015% ± 0.013), and schwannoma cells (0.121% ± 0.158)." (PMID 41607802, 2026). "Regarding the variable cell type, CD34+ cells isolated from cord blood exhibited the highest mean reprogramming efficiency (1.199% ± 0.529), compared to fibroblasts (0.040% ± 0.103), PBMCs (0.015% ± 0.013), and schwannoma cells (0.121% ± 0.158)." (PMID 41607802, 2026). "Those specimens reported to have schwannoma-like and neurofibroma-like features were selected for further characterization by morphology, immunohistochemical panel (CD34, S100, neurofilament triplet protein (immunostain) (NFTP), epithelial membrane antigen (EMA)), and confirmation as hybrid tumors." (PMID 26709712, 2016). "Additionally, CD34 or c-kit protein is useful to distinguish the schwannomas from GISTs11–13." (PMID 31608147, 2019). "In fact, the coexistence of desmin and SMA strongly supported the smooth muscle nature of the observed esophageal neoplastic lesions, while the constant negativity for CD34, CD117 and S-100 excluded other diagnostic hypotheses, including inflammatory fibroid polyps, GISTs and schwannomas." (PMID 24959231, 2014).
schwannoma (continued). "For example, inflammatory myofibroblastic tumors are always positive for SMA and ALK-1, leiomyomas are always positive for Desmin and Caldesmon, GIST is positive for CD117, CD34, and DOG-1, schwannomas are positive for S100, etc.." (PMID 39188678, 2024). "Immunohistochemical staining results of other benign schwannomas showed positivity for S‐100,26, 29, 30 SOX10, Vimentin, and GFAP, and negativity for SMA, EMA, CD34, and CD117." (PMID 36440500, 2023). "Histopathology revealed a mesenchymal tumor with immunohistochemical analysis suggestive of schwannoma (CD117-, CD34-, SMA-, and S100+)." (PMID 35371709, 2022). "Neural tumors such as schwannoma and neurofibroma can show focal positivity for BCL2 and CD34 and strong positivity for S100 protein." (PMID 34211794, 2021). "Schwannomas present negativity for SMA, Desmin, CD34, CD117 and positivity for S-100 protein and NSE." (PMID 30710876, 2019). "IHC staining of the 3 cases of hybrid schwannomas/perineuriomas showed positivity for S-100 protein in the schwannomatous areas while EMA and CD34 were positive in perineuromatous areas." (PMID 28526004, 2017). "Post-operative detailed histopathological examination showed benign schwannoma: CD117(−), S-100(+), GFAP(+), CD34(−), SMA(−), and Ki-67(+, little)." (PMID 27038921, 2016). "The pathological diagnosis was Schwannoma and immunohistochemical testing showed Vimentin (+), S-100 (+), MBP (+), CD56 (+), GFAP (+), Ki-67 (+), Desmin (−), SMA (−), EMA (−), CD34 (positive in tumor vessels)." (PMID 23432938, 2013). "Unlike schwannomas, neurofibromas demonstrate CD34 protein positive rather than SOX-10 strong peripheral staining seen in schwannomas." (PMID 40538849, 2025). "A brief immunohistochemical panel, consisting of anti-CD34, anti-Factor XIIIa, and anti-S-100, was performed to make the differential diagnosis between dermatofibroma and schwannoma, and to rule out dermatofibrosarcoma protuberans." (PMID 37032629, 2023). "However, given that spindle cells are present in a variety of neurogenic tumors, immunohistochemical staining with markers including S-100, SMA, CD34, and CD31 is necessary to conclusively diagnose a schwannoma." (PMID 38082359, 2023). "Immunohistochemically, schwannomas have positive S-100 antibodies with negative cytokeratins, CD34, and inhibins that play a pivotal role in the definitive diagnosis." (PMID 34058462, 2021). "Schwannomas test positive for S-100 protein and negative for desmin, smooth muscle actin, CD34, and CD117." (PMID 34410526, 2021). "Schwannomas are uniformly positive for S-100, occasionally positive for CD34, and negative for CD117, desmin, and SMA." (PMID 32685549, 2020). "In one case of schwannoma, we observed (non-published observations) varying sized strands of TCs/CD34+SCs between numerous cellular groups or lobules with characteristics of the Antoni A zone (including the presence of Verocay bodies)." (PMID 32560571, 2020). "Schwannomas are S-100 positive, but CD-34 and c-kit negative; most GISTs are s-100 negative, but CD-34 and c-kit positive." (PMID 31608147, 2019). "EUS-FNA was performed and spindle-shaped cells that were immunopositive for S-100 and negative for c-kit, CD34, and desmin were detected, resulting in a diagnosis of schwannoma." (PMID 30631851, 2018). "The observed dual histology of these hybrid tumors was further supported by a corresponding dual immunophenotype: schwannoma component stained S100 positive and CD 34 negative while neurofibroma component stained CD34 positive with variable S100 expression." (PMID 26709712, 2016). "Tumor cells that are positive for S-100 protein and negative for smooth muscle actin, c-Kit and CD34 support the diagnosis of a schwannoma." (PMID 22277785, 2012). "Additionally, immunohistochemistry revealed strong positivity for S100 and SOX10, which is typical of schwannomas, and negative staining for markers like c-KIT, DOG1, and CD34, which are associated with GISTs." (PMID 40507589, 2025).
schwannoma (continued). "The observed dual histology of these hybrid tumors was further supported by a corresponding dual immunophenotype: the schwannoma component was S100 positive and CD34 negative while the neurofibroma component contained CD34 positive fibroblasts and S100 protein-positive Schwann cells." (PMID 26709712, 2016). "As a contrast, a schwannoma is negative for both CD34 and CD117." (PMID 27038921, 2016). "Cellular schwannoma cells stain positive for S-100, may stain positive or negative for CD34 and stain negative for EMA." (PMID 24410763, 2014). "Schwannoma and neurofibroma are strongly reactive with S100 protein, while lacking CD34." (PMID 24179528, 2013). "Histopathological analysis revealed a schwannoma, with immunohistochemistry showing S-100 positivity and negative staining for C-KIT, CD34, actin, and desmin—key findings that helped differentiate it from other mesenchymal tumors, such as GIST or leiomyomas." (PMID 40507589, 2025). "Immunohistochemistry was positive for SOX10 and negative for CD34, DOG1, and desmin, confirming schwannoma." (PMID 41230329, 2025). "Immunohistochemically, the tumor was strongly positive for vimentin and S-100 protein, while negative for CD34 and CD117 (c-kit), consistent with the diagnosis of schwannoma." (PMID 40772163, 2025). "Schwannomas consistently express S100 and SOX10, while being negative for CD117, DOG1, and CD34, distinguishing them from GIST." (PMID 40507589, 2025). "Both neurofibroma and schwannoma are positive for SOX10 and S100 protein, negative for STAT6; meanwhile, neurofibroma is also positive for CD34." (PMID 41226013, 2025). "Immunohistochemically, HPCs typically express markers such as CD34, vimentin, CD99, and Bcl-2 while being negative for S100, which helps differentiate them from other spindle cell neoplasms like schwannomas or meningiomas." (PMID 39371697, 2024). "The diagnosis is confirmed through immunohistochemical studies, where schwannomas typically stain positive for S-100 and SOX-10, unlike CD34, CD117, and desmin, which are markers for leiomyomas." (PMID 39554676, 2024). "In all compartments including Verocay body-like areas, the tumor cells showed immunoreactivity for Factor XIIIa while they were negative for CD34 and S-100 antibodies, and the latter two excluded DFSP and schwannoma, respectively." (PMID 37032629, 2023). "Schwannoma differs from GIST as it is consistently negative for CD117 (c-kit), CD34 and DOG-1 which are usually positive in GIST." (PMID 38163055, 2023). "The parameters of schwannoma immunohistochemistry are based on positivity for S-100 protein and on the absence of staining for CD117, CD34, Desmin and specific muscle actin." (PMID 30710876, 2019). "For example, GISTs are positive for CD117, schwannomas are positive for S100 protein, and IMTs are positive for ALK and negative for CD34, whereas IFPs are not." (PMID 29855265, 2018). "The only case of schwannoma/neurofibroma was positive for S100 protein in both schwannomatous and neurofibromatous areas while EMA and CD34 were negative." (PMID 28526004, 2017). "This difference in immunophenotype is represented by the spindle cells of schwannomas showing strong diffuse positivity for S100 and an absence of staining for CD117, DOG1, CD34, desmin, SMA and actin." (PMID 25667620, 2015). "In contrast to GISTs, schwannomas are consistently negative for CD117 (KIT) and usually negative for CD34, CKs, smooth muscle actin and desmin, but strongly positive for S100 protein and vimentin." (PMID 25360169, 2014). "Leiomyomas are strongly positive for desmin and SMA, but negative for CD117 and CD34, while schwannomas show positivity for S100 protein, with a lack of CD117 and CD34 expression." (PMID 23833657, 2013). "Immunohistochemical studies revealed S100 protein positivity and the absence of staining for α smooth muscle actin (αSMA), CD34 and CD117, thereby establishing the diagnosis of benign schwannoma." (PMID 24088647, 2013).
schwannoma (continued). "Immunohistochemical studies revealed S100 protein positivity and the absence of staining for α smooth muscle actin (αSMA), CD34 and CD117, establishing the diagnosis of benign schwannoma." (PMID 24088647, 2013). "The absence of staining for CD34 and NFP, but strong positivity for S-100, supports the diagnosis of schwannoma as opposed to neurofibroma." (PMID 23320233, 2012). "Schwannomas tend to express S-100 but not CD117, and only rarely express CD34." (PMID 39533578, 2024). "The diagnosis of schwannoma is based on immunohistochemical staining of S-100 and vimentin positive and negative results of CD117 and CD34, whereas GISTs are usually positive for CD117, DOG1 and CD34, but S-100 is mostly negative." (PMID 31647020, 2019). "The diagnosis of schwannoma is based on positive immunohistochemical staining for S-100 protein and negative results for CD117, CD34, desmin, and smooth muscle actin (SMA), whereas GIST is typically positive for CD117, DOG-1, and CD34 but negative for S-100 protein." (PMID 26559271, 2015).